MTOR (mechanistic target of rapamycin kinase)
Diseases named in the same sentence as MTOR in open-access papers (continued):
Sharing a sentence is not in itself a finding about the gene and the disease.
gastric cancer (continued). "A recent study found that esomeprazole decreased protein levels of PI3K, AKT, mammalian target of rapamycin (mTOR), and HIF-1α in multiple gastric cancer cell lines." (PMID 35992826, 2022). "Luteolin, another component of MO, which has been found to reduce gastric cancer cells growth and cancer metastasis in vitro and in vivo via regulating Notch1, PI3K, AKT, mTOR, ERK, STAT3, and P38 signaling pathways." (PMID 35889404, 2022). "Aberrantly expressed miR-188-5p promoted gastric cancer metastasis by activating Wnt/β-catenin signaling and progression of acute promyelocytic leukemia by activating PI3K/AKT/mTOR signaling." (PMID 35008435, 2021). "For example, Pectolinarigenin induced gastric cancer cell apoptosis and autophagy through inhibiting PI3K/Akt/mTOR pathway." (PMID 33627124, 2021). "It has been reported that PD-1 blocks the Akt/mTOR signaling pathway and inhibits the glycolysis of CD8+ T cells in gastric cancer." (PMID 34659197, 2021). "Apoptosis and autophagy can be induced in the prevention of tumor growth of gastric cancer cells, and the related mechanisms involve PI3K/Akt/mTOR pathway." (PMID 33627124, 2021). "There is evidence that the PI3K/AKT/mTOR pathway mediates the function of m6A “writers” METTL3 and METTL14 in the progression of gastric cancer and retinoblastoma." (PMID 34088349, 2021). "Celastrol has been reported to induce autophagy and apoptosis in different tumor cells, such as glioma and gastric cancer via the ROS/JNK and AKT/mTOR signaling pathways." (PMID 34575981, 2021). "Since an individual miRNA can target several genes within the same cellular pathway, our analysis confirms that other oncogenic pathways were included in the “gastric cancer” pathway, such as ErbB, TGF-β, Wnt, MAPK, and mTOR pathways." (PMID 35008894, 2021). "In gastric cancer, SLC39A7 induces gastric cancer cell proliferation and migration and inhibits apoptosis via the AKT/mTOR signaling pathway." (PMID 34149917, 2021). "Mesenchymal stem cells (MSCs), found in the TME of gastric cancers, express IL-8, which induces PD-L1 expression in gastric cancer cells through STAT3 and mTOR signaling." (PMID 34063096, 2021). "Gambardella and coworkers found that NRF2 amplified the resistance to anti-HER2 drugs through the PI3K/AKT/mTOR/RPS6 pathway, and that ribosomal protein S6 (RPS6) inhibition decreased NRF2 expression and restored sensitivity in HER2-amplified gastric cancer." (PMID 34070502, 2021). "In the present study, we demonstrate that TSPAN9 blocks PI3K–Akt–mTOR signaling by interacting with PI3K, which enhances autophagy and leads to 5-FU resistance in gastric cancer cells." (PMID 31911756, 2020). "Taken together, our results indicated that berberine sensitized DDP-resistant gastric cancer cells to DDP via enhanced cell apoptosis and inhibited PI3K/AKT/mTOR signaling." (PMID 33362566, 2020). "Studies have demonstrated that phosphorylation of Akt and mTOR was increased in DDP-resistant gastric cancer cells and inhibition of PI3K/Akt pathway significantly attenuated CCL2-mediated DDP-resistance in gastric cancer." (PMID 33362566, 2020). "In a recent study, it was reported that IL-8 activates mTOR and increases endogenous c-MYC production, thereby inducing PDL1 expression in gastric cancer." (PMID 32615949, 2020). "Ant-proliferative activity of the dual AKT/mTOR inhibitor, BEZ235, correlated with a dose-dependent increase of gastric cancer cells in the G1 phase of the cell cycle and cyclin D1 downregulation." (PMID 33659215, 2020). "Taken together, TIPRL acts as a novel metastasis suppressor in gastric cancer, at least in part, through regulating AMPK/mTOR signaling, likely representing a promising target for new therapies in gastric cancer." (PMID 32719745, 2020).
gastric cancer (continued). "Functional experiments revealed that BAG2 knockdown in gastric cancer cells inhibited the proliferation, invasion and migration of cells through AKT/mTOR and extracellular regulated kinase (ERK) pathways." (PMID 32082999, 2020). "Recent evidence has shown CXCR4-dependent mTOR signaling in pancreatic cancer, gastric cancer, and T-cell leukemia cells; in fact, CXCR4 and mTOR inhibitors have been reported to impair human renal cancer migration." (PMID 32260318, 2020). "Previous study indicated that miR-520a-3p diminished gastric cancer cell glycolysis and proliferation by forming feedback with AKT1/mTOR/HIF1α pathway." (PMID 33768113, 2020). "In a mouse intestinal gastric cancer model, mTOR C1 was overactivated, and the activation of the PI3K/mTOR C1 pathway was necessary for the occurrence of inflammation-related gastrointestinal tumors." (PMID 33537033, 2020). "We first investigated the antitumor effects of 2,6-DMBQ on gastric cancer PDX models and the results showed that 2,6-DMBQ significantly reduced gastric tumor growth by inhibiting the mTOR/p70S6K signaling pathway." (PMID 32517736, 2020). "Several signaling pathways can be activated by SNHG6, including the MAPK and JNK pathway in gastric cancer, PI3K/AKT/mTOR pathway and TGF-β/Smad pathway in colorectal cancer." (PMID 32655318, 2020). "Among these, the Wnt signaling pathway, the mTOR signaling pathway and the NOD-like receptor signaling pathway have been proven to be related to gastric cancer with H. pylori infection." (PMID 32915799, 2020). "In conclusion, this study showed that TSPAN9 and PI3K bind to each other in gastric cancer cells, which inhibits the activity of the PI3K–Akt–mTOR pathway and consequently enhances the level of autophagy and promotes 5-FU resistance." (PMID 31911756, 2020). "To further demonstrate SILAC quantitation with the Affi-BAMS workflow, we examined the response of the human gastric carcinoma cell line, MKN45, to rapamycin (an inhibitor of mTOR signaling)." (PMID 32188029, 2020). "In hepatocarcinoma and gastric cancer cells, SB365 suppressed the PI3K/Akt/mTOR pathway, which negatively regulates autophagy." (PMID 31491945, 2019). "Similarly, a recent study confirmed that circNRIP1 could be transmitted by exosome connection between gastric cancer (GC) cells, and exosomal circNRIP1 sponges miR-149-5p to affect the AKT1/mTOR signaling pathway and to promote the proliferation, migration and metastasis in gastric cancer." (PMID 31277663, 2019). "In gastric cancer cells and multiple myeloma, AMPK pathway is activated via phosphorylation and subsequently inactivates mTOR and its downstream targets including p70S6K and 4E-BP1 after tigecycline treatment, thereby inducing cell autophagy." (PMID 31336613, 2019). "In gastric cancer, circNRIP1 sponging microRNA-149-5p regulated the AKT1/mTOR pathway to promote progression through." (PMID 31857500, 2019). "We found that Zey suppressed the metastasis of gastric cancer cells by decreasing protein levels of MMP-2 and MMP-9 and inhibiting the phosphorylation of AKT, ERK, and mTOR." (PMID 30150551, 2018). "Together, we provided a novel regulatory mechanism for ANRIL in gastric cancer, in which ANRIL silence down-regulated BMI1 via miR-99a, along with activation of the apoptotic pathway and inhibition of the Notch and mTOR pathways." (PMID 30156609, 2018). "In sinularin-treated gastric cancer (AGS and NCI-N87) cells, the phosphoinositide 3-kinase (PI3K)/AKT/mammalian target of rapamycin (mTOR) signaling was inactivated and lead to apoptosis." (PMID 29642488, 2018). "Drug screening studies in isogenic CDH1−/−-mutant mammary epithelial MCF10A and c.1380delA CDH1-mutant gastric cancer cells show considerable overlap in sensitivity to PI3K, mTOR, or ALK/ROS-1 like tyrosine kinase inhibition." (PMID 29468433, 2018). "Therefore, targeting DDX5/mTOR/S6K1 might be a novel approach for the treatment of gastric cancer." (PMID 28216662, 2017).
gastric cancer (continued). "Recently, it has been reported that harmine induced autophagy in MGC-803 and SGC-7901 cells by the inhibition of Akt/mTOR/p70S6K, the activation of AMPK pathway and mitochondrial pathway in human gastric cancer cells." (PMID 29197358, 2017). "According to our previous study, some of the gastric cancer-related mRNAs were co-expressed with UCA1 and were involved in the PI3K-Akt-mTOR signaling pathway." (PMID 29212166, 2017). "Together, the resulted showed that UCA1 affected malignant progression of gastric cancer cells partly through p-AKT3 and p-mTOR in the PI3K-Akt-mTOR signaling pathway." (PMID 29212166, 2017). "We first aimed to validate the increased activity of the dual PI3K/mTOR and topoisomerase II inhibitors in hereditary c.1380delA CDH1 SB.mhdgc-1 gastric cancer cells in an extended panel of sporadic gastric cancer cell lines." (PMID 28460635, 2017). "Overexpression of lncRNA PVT1 in gastric carcinoma promoted the development of multidrug resistance and influenced the expression of MDR-related proteins (MDR1, MRP1, mTOR, and HIF-1a)." (PMID 29046366, 2017). "Our previously studies found that Klotho protein inhibited the activation of IRS-1 / PI3K / Akt / mTOR and ERK / p70s6k and downstream signaling pathways in gastric cancer and liver cancer cells, mainly through the inhibition of IGF-1R phosphorylation." (PMID 27779100, 2016). "miR-1271 regulates cisplatin resistance of human gastric cancer cell lines by targeting IGF1R, IRS1, mTOR, and BCL2." (PMID 32309578, 2016). "By summarizing data on HER2, VEGR, EGFR, mTOR, MET, and other common cancer targets or signaling pathways, this review attempts to expound the advance of molecular targeted therapy for gastric cancer in recent years." (PMID 26880889, 2016). "Recent research indicated that upregulation of PVT1 inhibited apoptosis in gastric cancer cell lines, increased the expression of MDR1, MRP, mTOR, and HIF‐1α, promoted the development of multidrug resistance." (PMID 27794184, 2016). "The mammalian target of rapamycin (mTOR) and phosphorylated mTOR (p-mTOR) occurring downstream in the PI3K/Akt/mTOR pathway, are regarded as potential prognostic markers for gastric cancer (GC)." (PMID 28005970, 2016). "Our findings suggest that sinularin inhibits gastric cancer cell proliferation and induces apoptosis through mitochondrial dysfunction and inhibition of the PI3K/Akt/mTOR signaling pathway." (PMID 27472346, 2016). "The immunohistochemistry stainings of p-Akt, p-mTOR, VEGF-C and VEGF-D in 55 gastric cancer clinical specimens were shown." (PMID 25884175, 2015). "Key proteins in mTOR pathway and MMP7 expressions were unfavorable prognostic factors for gastric cancer, while PTEN expression was a favorable prognostic factor." (PMID 25909163, 2015). "In the study, we further confirmed the relationship of Akt/mTOR, VEGF-C/-D and LVD in gastric cancer in situ." (PMID 25884175, 2015). "This study aims to demonstrate the relationship between Akt/mTOR pathway and VEGF-C/-D in gastric cancer." (PMID 25884175, 2015). "In this study, we aim to demonstrate the relationship between Akt/mTOR pathway and VEGF-C/-D in gastric cancer." (PMID 25884175, 2015). "In the present report, we investigated the effects of licochalcone A (LA), a flavonoid extracted from licorice root, on the PI3K/AKT/mTOR and MAPK activation pathways in human gastric cancer BGC-823 cells." (PMID 25981581, 2015). "Researchers have widely studied p-mTOR, pS6, p4EBP1, PTEN, MMP7, and DCN expression in human solid cancer tissues, including gastric cancer." (PMID 25909163, 2015). "The positive staining rates of p-Akt, p-mTOR, VEGF-C and VEGF-D in 55 gastric cancer clinical specimens were 74.54%, 85.45%, 72.73% and 58.18%." (PMID 25884175, 2015). "PTEN and AMPK proteins were frequently inactivated and p-mTOR, pS6, p4EBP1, and MMP7 proteins were frequently downregulated in human gastric cancer." (PMID 25909163, 2015).
gastric cancer (continued). "In human gastric cancer (GC), PI3K/Akt and mTOR are known to be activated in approximately 30% and 60% of patients, respectively." (PMID 25886409, 2015). "It suggested that both Akt/mTOR pathway and VEGF pathway involved in lymphangiogenesis and lymphatic vessel metastasis in gastric cancer." (PMID 25884175, 2015). "Protein expression levels of pAMPKα, p-mTOR, pS6, p4EBP1, MMP7, DCN and PTEN were analyzed in 39 resected primary gastric cancer samples." (PMID 25909163, 2015). "We evaluated expression of leptin-signaling-related proteins (leptin, leptin-receptor, pSTAT3, ERK, pAkt, mTOR and HIF-1 alpha) and the EBV infection status within cancer cells, and determined their clinicopathological significance in gastric carcinomas." (PMID 26147886, 2015). "The mRNA expression levels of GOLPH3, mTOR, Akt, p70S6 and 4E-BP1 in gastric cancer, carcinoma-adjacent and paired normal tissue were analyzed using RT-PCR." (PMID 25286393, 2014). "This current study shows that MK-2206 (an Akt inhibitor) and RAD001 (a mTOR inhibitor) can be combined to synergistically inhibit PI3K/Akt/mTOR signaling and gastric cancer cell growth." (PMID 24416349, 2014). "The protein expression levels of GOLPH3, p-AKT, p-mTOR, p-p70S6 and p-4E-BP1 in gastric cancer tissues were also significantly higher than in carcinoma-adjacent and paired normal tissues." (PMID 25286393, 2014). "The PI3K pathway is commonly activated in advanced gastric carcinoma and survival signals induced by several receptors are mediated mainly by the PI3K/Akt/mTOR pathway." (PMID 25003395, 2014). "BEZ235, a novel inhibitor of PI3K and mTOR, exerts antitumor effects against gastric carcinoma and enhances the effects of nab-paclitaxel through inhibition of cell proliferation and modulation of the PI3K/mTOR pathway." (PMID 25003395, 2014). "The effect of BEZ235 on the PI3K/mTOR signaling pathway was investigated using SNU16, NCI-N87 and AGS gastric cancer cell lines." (PMID 24042258, 2013). "Klotho is a tumor suppressor in gastric cancer, which regulates IGF-1R phosphorylation and the subsequent activation of IRS-1/PI3K/Akt/mTOR signaling, tumor cell proliferation, apoptosis, and autophagy." (PMID 23432957, 2013). "Phosphorylated mTOR and 4E-BP1 levels were elevated in gastric cancer cells and tumor tissues by nab-paclitaxel." (PMID 24042258, 2013). "This SNP, which effectively influenced the expression of mTOR, may be a new biomarker of early diagnosis of gastric cancer and a suitable indicator of utilizing mTOR inhibitor for treatment of GC." (PMID 23555892, 2013). "Our findings suggest that BEZ235 exerts some antitumor effects against gastric cancer and enhances effects of nab-paclitaxel through inhibition of cell proliferation and modulation of the PI3K/mTOR pathway." (PMID 24042258, 2013). "Results indicate that NVP-BKM120, a pan-class I PI3K inhibitor, is able to inhibit mTOR downstream activation, but induces the phosphorylation of AKT and the activation of p-ERK or p-STAT3 in KRAS mutant gastric cancer cells." (PMID 22159814, 2012). "However, several NPs such as Thymoquinone, β-Elemene, and Salidroside have been reported to exhibit a close correlation between their anti-gastric cancer properties and the inhibition of cell apoptosis mediated by the PI3K/AKT/mTOR signaling pathway." (PMID 40066330, 2025). "Accumulating literature highlights that many of the bioactive components possess anticancer properties, exemplified by Caffeine and Theophylline, which have been reported to induce apoptosis and autophagy in gastric cancer cells by activation of PTEN and inhibition of PI3K/Akt/mTOR pathway." (PMID 40599331, 2025). "In gastric cancer, for example, exosomes contain elevated levels of circNRIP1, which promotes pulmonary and peritoneal metastasis through EMT by blocking miR‐149‐5p and activating the AKT/mTOR axis." (PMID 40318053, 2025).
gastric cancer (continued). "Therefore, the aim of this study is to determine if Tempol exerts anti-cancer activity in HT29 colon and CRL-1739 gastric cancer cells through the induction of apoptosis and oxidative stress and the suppression of MAPK and Akt/mTOR signaling pathways." (PMID 40729043, 2025). "Previous studies have shown that H3K18la-mediated VCAM1 expression promotes gastric cancer progression and metastasis via the AKT‒mTOR‒CXCL1 axis; lactic acid accumulation resulting in H3K18la promotes PD-L1 transcription, thereby mediating the immune escape of gastric cancer cells." (PMID 40796546, 2025). "CCL21 has been found to be overexpressed in patients with gastric cancer, and further studies have shown that it upregulates the expression of MALAT1, activates the mTOR signaling pathway, and promotes migration, invasion, and epithelial–mesenchymal transition (EMT) of gastric cancer cells." (PMID 39840050, 2024). "Activation of the PI3K/Akt/mTOR pathway by BCAT1 may also promote the proliferation, invasion, and angiogenesis of gastric cancer cells." (PMID 38309289, 2024). "Likewise, mTOR inhibitors such as 2,6-DMBQ (AZD8055) has also been previously reported for their inhibitory efficacy in gastric cancer." (PMID 38962317, 2024). "Everolimus, as an mTOR inhibitor, reversed the METTL3-induced proliferation in a dose-dependent manner, which may be used in the treatment of m6A/METTL3-high gastric cancer." (PMID 39009956, 2024). "Berberine also enhances autophagy in glioblastoma by modulating the AMPK/mTOR/unc-51-like autophagy-activating kinase 1 (ULK1) pathway and inhibits the proliferation of human gastric cancer cells by deactivating the MAPK/mTOR/p70S6K/Akt signaling cascade both in vivo and in vitro." (PMID 39202856, 2024). "However, a gastric cancer study identified connections between mTOR/PKM2 and STAT3/c‐Myc signaling pathways, constituting a molecular network that jointly regulates the energy metabolism in gastric cancer." (PMID 39584783, 2024). "Specifically, treatment of CLDN18.2-positive gastric cancer cells with αCLDN18.2-MMAE led to a decreased phosphorylation of Akt, mTOR, and two critical downstream effectors, 4E-BP1 and p70S6K, indicating the inactivation of the Akt/mTOR pathway." (PMID 39227365, 2024). "MENK reduced the expression of PI3K, p-AKT, and mTOR, suggesting that MENK could inhibit PI3K/AKT/mTOR signaling in gastric cancer." (PMID 39003350, 2024). "Furthermore, the study explored the impact of GKN1 on gastric cancer xenograft tumor mice, specifically focusing on inflammation, cell proliferation, and PI3K/Akt/mTOR signaling pathways." (PMID 39524138, 2024). "BCAT1 could promote gastric cancer cell invasion, proliferation, and angiogenesis through PI3K/AKT/mTOR signaling pathway." (PMID 37460470, 2023). "Similarly, FGFR2 activates the PI3K/AKT/mTOR axis and its downstream TSP1, which regulates migration and invasion of gastric cancer cells." (PMID 37750089, 2023). "In gastric cancer, PTPN14 promoted the PI3K/AKT/mTOR pathway." (PMID 36898991, 2023). "The following studies have reported an upregulation of PD-L1 via the activation of mTOR in several cancer cell models: In a gastric cancer organoid model, the expression of PD-L1 induced by the hedgehog transcriptional effector GLI was mediated via the activation of the mTOR pathway." (PMID 37834467, 2023). "Moreover, bufalin can inhibit gastric cancer development and progression through PI3K/AKT/mTOR signalling pathway via BFAR." (PMID 38082327, 2023).